LEP (leptin)
Diseases named in the same sentence as LEP in open-access papers (continued):
Sharing a sentence is not in itself a finding about the gene and the disease.
metabolic disorders (continued). "In addition to metabolic disorders, leptin levels also relates to chronic diseases such as cardiovascular disease, chronic kidney disease, mood disorders, and other diseases." (PMID 36698957, 2022). "Quercetin may have a role in the management of metabolic disorders via different mechanisms, such as increasing adiponectin and decreasing leptin and antioxidant activity through the NF-κB signalling pathway." (PMID 36061816, 2022). "Adiponectin and leptin are the main cytokines of adipose tissue, which may influence the development of metabolic diseases and carcinogenesis." (PMID 35628118, 2022). "We would predict that patients with increased levels of leptin, for example obese patients or patients with metabolic disorders might be more likely to have less efficient wound healing." (PMID 36424766, 2022). "Moreover, leptin-impaired signal transduction is closely related to metabolic diseases, including obesity and type 2 diabetes." (PMID 36337626, 2022). "Leptin is mainly expressed in adipocytes and has pleiotropic effects in the regulation of energy homeostasis, neuroendocrine function, and immune response, so leptin pathway signaling disruption may lead to metabolic disorders." (PMID 35409202, 2022). "Interruption of leptin surge time impairs the development of the melanocortin system, leading to changes in the hypothalamic feeding circuit, which may lead to metabolic disorders in adulthood." (PMID 32623698, 2021). "Increased leptin and resistin levels result in immune cell infiltration into the adipose tissue through the increase of vascular permeability, which subsequently elevates oxidative stress and inflammatory responses thereby leading to metabolic disorder." (PMID 33643424, 2021). "We may also speculate that reduced leptin secretion from adipose and/or circulating immune cells may represent a new target to treat inflammatory and metabolic diseases." (PMID 34360753, 2021). "Targeting leptin sera levels and secretion from PBMCs could represent a new therapeutic strategy to counteract metabolic diseases such as T2DM." (PMID 34360753, 2021). "Human LEP is located on chromosome7q31.3, and its translational product is leptin, which plays a decisive role in the regulation of human appetite and results in severe metabolic disorders." (PMID 34589546, 2021). "Leptin, a hormone that is primarily derived from adipose tissue, possesses diverse and complex metabolic signaling potential, and there is a growing appreciation that elevated plasma leptin levels are related to numerous metabolic disorders." (PMID 34830465, 2021). "As part of a mechanistic study for ANGPTL6 regulation, we have previously found that exercise training lowers serum ANGPTL6 levels in sedentary subjects not having a medical history of metabolic diseases, and its alteration is linked to leptin." (PMID 33668309, 2021). "Due to the opposite metabolic effects of leptin and adiponectin, the leptin/adiponectin ratio (L/A ratio) has been proposed as a useful marker for metabolic disease, and may be more strongly associated with CVD risk than leptin or adiponectin alone." (PMID 34122163, 2021). "Leptin is reduced and higher ghrelin levels are observed in subjects with shorter sleep durations, as regularly seen in shift workers, leading to a state of increased metabolic stress, which serves as a driver for development of metabolic diseases." (PMID 33808424, 2021). "This is attributed to the interference of work on physiological processes such as the circadian rhythm, leading to changes in the secretion of melatonin, growth hormone, prolactin, leptin and glucocorticoids, leading to weight gain and the onset of metabolic disorders." (PMID 33688327, 2021).
metabolic disorders (continued). "Metabolic disorders and insufficient homeostatic compensatory mechanisms involving leptin during pregnancy play a decisive role in the development of pre-eclampsia (PE) and give rise to compromised intrauterine growth conditions and aberrant birth weight of offspring." (PMID 33925454, 2021). "Besides, our findings corroborate with our previous results in which high leptin and CRP levels were associated with activated oxidative stress and systemic inflammation in overweight adolescents with PCOS complicated with metabolic disorders." (PMID 32545404, 2020). "Besides energy homeostasis, leptin plays a role in immune regulation and the inflammatory response and is involved with metabolic disorders and neoplastic development." (PMID 32629916, 2020). "In addition to maintaining a healthy lifestyle and eating with a healthy diet, early diagnosis of the markers of metabolic disease is also essential which mainly include glucose, uric acid, leptin, and various vitamins." (PMID 32850664, 2020). "The development of leptin resistance in the central nervous system may contribute to this metabolic disorder." (PMID 32846917, 2020). "Asprosin concentration before WBC correlated positively with metabolic disorder risk factor levels, and the change in asprosin concentration after 20 WBC correlated negatively with metabolic disorder risk factor levels: fasting glucose, AIP, and the leptin/adiponectin index." (PMID 31510055, 2019). "Indeed, the alteration of leptin action early in life has long-term impact on energy homeostasis and contributes to metabolic diseases." (PMID 30845245, 2019). "To summarize, the collected data suggest that the leptin promoter is hypomethylated in metabolic disorders as well as also being correlated with some important biochemical and anthropometric parameters or serve as a potent marker of response to dietary intervention." (PMID 31408957, 2019). "More importantly, the use of ob/ob mice with intrinsic leptin deficiency in the metabolic disease should always be cautious, as the involvement of leptin in multiple metabolic signaling pathways should not be overlooked." (PMID 30885145, 2019). "In the current study, it is reasonable to speculate that low-grade inflammation was successfully established due to leptin upregulation and plasma glucose elevation, which indicate initiation of a metabolic disorder." (PMID 31311115, 2019). "Still, GDM-induced changes of the LEP methylation in SAT may contribute to metabolic disorders to some extent." (PMID 31408957, 2019). "This pre-hibernation state of “leptin resistance,” which has been directly observed and quantified in black bears and brown bats, closely mirrors the presentation of patients with metabolic disorders." (PMID 31156558, 2019). "The role of leptin as an inflammatory adipokine in metabolic disorders is well studied." (PMID 29760587, 2018). "Presently, antagonists of leptin have been developed to treat metabolic disorders." (PMID 30584543, 2018). "Efforts towards identifying potential biomarkers of metabolic disease-risk did not result in any strong candidates, albeit leptin levels were altered in exposed animals." (PMID 29321614, 2018). "Thus, leptin has emerged as a significant pathological component in the development of metabolic disorders." (PMID 29910742, 2018). "While causal factors for adverse neonatal anthropometric outcomes are intensively studied, determinants of cord-blood insulin and leptin are less considered in clinical studies, although probably even more important mechanistically for the long-term development of metabolic disorders." (PMID 29925339, 2018). "In summary, testosterone may use a novel pathway to complement leptin signaling to regulate glucose and lipid metabolism, and thus offers a new therapeutic target to treat metabolic disorders." (PMID 29895265, 2018).
metabolic disorders (continued). "Increased visceral fat is related with metabolic diseases and inflammation, in association with an increased concentration of pro-inflammatory leptin, TNF-α, and IL-6 by increased adipose tissue, rather than subcutaneous fat." (PMID 30558262, 2018). "Besides energy regulation, leptin has immune system-related roles involving immune regulation, and inflammatory response, which contribute to metabolic disorders and neoplastic cell growth." (PMID 28182687, 2017). "The effects of SA on adiponectin and leptin indicated that it could improve cardiometabolic indices, since these markers are predictors of metabolic diseases." (PMID 26688813, 2015). "According to our study results, distribution of the G276G, G276T, and T276T genotypes and frequency of the 276T and 276G alleles of the leptin gene were not different in AO patients with or without metabolic disorders." (PMID 26504811, 2015). "Moreover, the intake of adecuate amounts of leptin during the suckling period has been proposed as one of the strategies for reversing the effects of metabolic disorders induced as a consequence of developmental programming." (PMID 25766068, 2015). "New miRNAs modulated by leptin could open important therapeutic perspectives for controlling metabolic disorders." (PMID 25999818, 2015). "Furthermore, in women with AO and metabolic disorders with the R223R genotype, leptin levels were higher than those in women, carriers of the 223Q allele of the LEPR gene (60.744 ± 5.581 ng/mL and 47.521 ± 3.243 ng/mL, resp.; p = 0.045)." (PMID 26504811, 2015). "Taken together, our findings suggest that MTMR14 deficiency evokes severe inflammation via the up-regulation of TNF-α and IL-6, and the metabolic disorders may depend on elevated leptin and decreased adiponectin." (PMID 26697164, 2015). "It remains unclear how leptin contributes to stress induced metabolic disorders and more studies are required in order to dissociate the interactions between central vs. peripheral leptin and glucocorticoids in response to stressful stimuli." (PMID 23898237, 2013). "This study reveals leptin resistance as an early marker of metabolic disorders that appears before any evidence of body weight increase in IUGR rats but whose mechanisms could depend of nutritional environment of the perinatal period." (PMID 22291999, 2012). "Leptin resistance represents an early marker of metabolic disorders whose mechanisms could depend of nutritional environment of the perinatal period." (PMID 22291999, 2012). "Consequently, impaired leptin and/or insulin signaling activation, as observed in db/db mice, has been proposed as potential link between behavioral and metabolic disorders." (PMID 21949705, 2011). "Importantly, with the treatment of leptin in these animals, there was the restoration of Pomc mRNA levels, underscoring the dynamic regulation of Pomc by leptin-induced changes in miRNAs, positioning them as potential therapeutic targets for metabolic disorders." (PMID 41040868, 2025). "Given the role of IGF-1 in metabolic regulation, we hypothesize that improvements in insulin sensitivity and liver histopathology following exogenous leptin therapy would be associated with changes in IGF-1 levels, which may correlate with improvements in metabolic disease." (PMID 40520449, 2025). "In addition to the relationship of leptin with adipose tissue and serum testosterone, many other factors and multiple metabolic disorders may condition leptin levels in CKD patients." (PMID 39062887, 2024). "In the present study, T3, T4, insulin, GLP-1, GHRP, GH, SS and leptin were not significantly altered by the experimental diets, indicating that neither dietary protein level reduction nor fatty acid supplementation caused the metabolic disorders." (PMID 37239844, 2023). "Therefore, modulation of leptin levels may be used in multiple aspects of metabolic disorders and may have a wider range of potential applications." (PMID 37400922, 2023).
metabolic disorders (continued). "The PTP1B and TC-PTP phosphatases, being negative regulators of insulin and leptin signaling, are involved in the development of insulin and leptin resistance and mediate an increase in appetite, and the accumulation of excess adipose tissue in metabolic disorders." (PMID 36901928, 2023). "Adiponectin and leptin are the main cytokines of adipose tissue, affecting insulin resistance, lipolysis, and inflammatory pathways, which may influence the development of metabolic diseases and carcinogenesis." (PMID 35628118, 2022). "Also, it has been suggested that impaired adipose tissue function due to the dysregulation of leptin and adiponectin may be involved in the induction of oxidative stress and the development of metabolic disorders." (PMID 36479221, 2022). "This suggests that sexual dimorphism of fat tissue and leptin should be considered from an early age for the design and analysis of future research involving prepubertal children, which will contribute to improving knowledge, understanding and prevention of metabolic diseases from childhood." (PMID 36064746, 2022). "Thus, metabolic disorders could exacerbate psoriatic skin inflammation, presumably via increased palmitic acid and leptin levels." (PMID 35457132, 2022). "Information on insulin, leptin, and cytokine signaling pathways within the CB might be of key importance and have significant clinical relevance as it might unravel therapeutic targets for the treatment of metabolic diseases." (PMID 32756352, 2020). "Furthermore, the lack of association between DNA methylation and plasma leptin or metabolic disease markers only supports the previous notion about initial methylation changes in SAT." (PMID 31408957, 2019). "However, in persons with metabolic disorders, adipocytes are hypertrophied and secrete pro-inflammatory adipokines including leptin, tumor necrosis factor-α, angiotensinogen, and interleukin-6, which aggravate insulin resistance and exert pro-atherosclerotic effect." (PMID 31236708, 2019). "Since leptin is a pro-inflammatory adipokine and hyperleptinemia in leptin resistance may induce chronic inflammation, future research should fully elucidate the role of leptin resistance in the pathogenesis of metabolic disorders." (PMID 31408957, 2019). "Therefore, in this review, we focused on recent achievements in the field of the epigenetic regulation of leptin as well as leptin-induced epigenetic phenomena in metabolic disorders such as the adipogenesis, fetal, and early postnatal programming of metabolism." (PMID 31408957, 2019). "Hence, modifications of the LEP methylation may also appear as an adverse effect of preterm delivery therapy and, thereby, contribute to later life metabolic disorders." (PMID 31408957, 2019). "For example, changes in leptin signaling during development could then affect the organization of critical neural circuits that regulate energy homeostasis, favoring the incidence of metabolic diseases later in life." (PMID 30694175, 2019). "Although we found subtle changes to some key factors, including leptin and glucagon levels in the blood, the study did not reveal strong evidence for heightened risk of metabolic disease or a propensity for weight gain, or any strong new candidates to serve as biomarkers." (PMID 29321614, 2018). "Same patterns of morphological changes, UCP1 expression and leptin translocation were observed in hADSCs and primary mouse BM-derived stem cells, indicating that MSCs provide a source of thermogenic beige adipocytes for human brown cell-based approaches to treat metabolic diseases." (PMID 29563605, 2018). "Due to the opposite metabolic effects of leptin and adiponectin, the leptin/adiponectin ratio (L/A ratio) has been proposed as a useful marker for metabolic disease and may be more strongly associated with T2DM risk and first CV event than leptin and adiponectin alone." (PMID 28068986, 2017).
metabolic disorders (continued). "Since it is evident that adiponectin protects and leptin accelerates the development of atherosclerotic diseases we can speculate that these adipokines may be the link between smoking and cardiovascular and metabolic diseases." (PMID 26869871, 2015). "Interestingly, detailed metabolic and molecular phenotyping in clinical studies have indicated that, inflammasome is a crucial link between BPH and metabolic disorders, since the inflammasome controls the energy expenditure and adipogenic gene expression including that of adipocyte hormone leptin." (PMID 25991911, 2015). "Thus, larger and durable cohort studies are required to assess whether the alterations observed in serum leptin and adiponectin concentration after abstinence from smoking exert a protective effect against cardiovascular disease and metabolic diseases." (PMID 26869871, 2015). "Therefore, the Westernized breakfast pattern may decrease risks of these metabolic diseases by lowering circulating leptin and PAI-1levels." (PMID 26058488, 2015). "Improvements in VO2max and MFO via leptin mediation suggest that the MedDiet could be particularly beneficial in training programs aimed at enhancing aerobic performance and utilizing fat as an energy substrate, with applications in both endurance sports and the prevention of metabolic disorders." (PMID 40507170, 2025). "It is known that the gut microbiota and microbial products such as postbiotics can interact with host endocrine system indirectly to alter hormone responses to catecholamines, leptin, and GLP-1 among other hormones relevant to metabolic disease." (PMID 39235984, 2025). "A positive IRSN-leptin relationship, particularly in cows with subclinical ketosis, aligns with prior studies connecting insulin and IRSN in metabolic disorders." (PMID 39109340, 2024). "Most importantly, we will focus on the novel regulation of leptin by AMPK, and the possible therapeutic relevance of short-term, cell-specific AMPK modulation in metabolic disease." (PMID 38314646, 2024). "Further studies are needed to evaluate the role of cord leptin and other biomolecule levels in the future development of T2DM and other metabolic diseases in GDM mothers and offspring." (PMID 37510870, 2023). "Considering the multiple functions of leptin derived either from the placenta or from the fetal/neonatal adipocytes and its greatly elevated level during the perinatal period, one can assume that defective leptin signalization may contribute to the development of metabolic disorders in later life." (PMID 37507894, 2023). "VAT is active in releasing bio-active factors such as leptin, adiponectin, tumor necrosis factor-α, interleukin-6, interleukin-8, and MCP-1 that are involved in the pathogenesis of CVD, metabolic disorders, and T2DM." (PMID 37964956, 2023). "Moreover, the observation that circulating insulin and leptin rhythms are altered in response to circadian disruption in a manner consistent with metabolic disease supports the notion that an endocrine signal may provide a mechanistic link between circadian rhythms and metabolic health." (PMID 37284222, 2023). "The importance of leptin in PCOS-related endocrine and metabolic disorders has been gradually recognized." (PMID 35355566, 2022). "In children, EGFL6 expression was positively correlated to parameters of AT dysfunction and metabolic disease such as macrophage infiltration into AT, hs-CRP, leptin levels, and HOMA-IR." (PMID 35457174, 2022). "To confirm the effects of MG741 on metabolic disorder markers, we measured fasting blood glucose levels, serum levels of insulin, ALT, AST, leptin, total cholesterol, LDL-cholesterol, HDL-cholesterol, liver weight, and liver triglyceride levels." (PMID 35565930, 2022). "AGF, a known peripheral activator of energy expenditure, is determined by leptin in mice hepatocyte, and serum AGF level is paradoxically increased in human patients with metabolic disease due to compensation." (PMID 33810547, 2021).